CHID1 (chitinase domain containing 1)
Description:
Saccharide- and LPS-binding protein with possible roles in pathogen sensing and endotoxin neutralization. Ligand-binding specificity relates to the length of the oligosaccharides, with preference for chitotetraose (in vitro).
Synonyms: SI-CLP; GL008; MGC3234; FLJ42707; SICLP
Tractability: Antibody: UniProt places it where antibodies can reach, with high confidence; its Gene Ontology location is reachable by antibodies, with high confidence; UniProt predicts a signal peptide or a membrane-spanning region. PROTAC: ubiquitination databases record sites on it; its protein half-life has been measured.
Gene: Protein-coding gene on chromosome 11 (867,331 to 915,579, reverse strand). Ensembl gene ENSG00000177830.
Subcellular location: Secreted; Lysosome
Subcellular location (Human Protein Atlas): Intermediate filaments; Nucleoplasm
Pathways (Reactome):
Hemostasis: Platelet degranulation
Gene Ontology:
Molecular function: oligosaccharide binding; protein binding; chitin binding
Biological process: negative regulation of cytokine production involved in inflammatory response; carbohydrate metabolic process
Cellular component: extracellular exosome; extracellular region; late endosome; lysosome; membrane; nucleus; trans-Golgi network; endomembrane system; lysosomal lumen
Genetic constraint (gnomAD): Loss-of-function variants: 41 observed, 52.32 expected, observed/expected ratio (o/e) 0.78, 90% interval 0.61 to 1.02. The upper end of that interval is the gene's LOEUF score, 1.02, which puts it in group 4 of 6, group 1 being the genes least tolerant of losing a copy. Missense variants: 476 observed, 505.93 expected, observed/expected ratio (o/e) 0.94, 90% interval 0.87 to 1.01. Synonymous variants: 211 observed, 208.23 expected, observed/expected ratio (o/e) 1.01, 90% interval 0.9 to 1.14.
Homologues: Orthologues: chimpanzee CHID1 (99% identical), macaque CHID1 (99% identical), rat Chid1 (91% identical), dog CHID1 (90% identical), mouse Chid1 (90% identical), guinea pig CHID1 (89% identical), pig CHID1 (72% identical), tropical clawed frog chid1 (59% identical), zebrafish chid1 (55% identical), Drosophila melanogaster CG8460 (41% identical), Caenorhabditis elegans chil-14 (23% identical). Paralogues in human: CHIA (19% identical), CHI3L2 (19% identical), CHIT1 (18% identical), OVGP1 (16% identical), CHI3L1 (15% identical), CTBS (15% identical).
Diseases named in the same sentence as CHID1 in open-access papers:
CHID1 is named in the same sentence as 18 diseases in open-access papers, as found by Europe PMC text mining. Sharing a sentence is not in itself a finding about the gene and the disease. The quoted sentences say what the papers report.
breast carcinoma (2 papers, 2020 to 2021). "It was demonstrated that forced overexpression of CHID1 in TS/A breast cancer cells led to delayed tumor growth, and this phenomenon was associated with decreased infiltration of the tumors by macrophages." (PMID 33466316, 2021). "While there is no published data on the role of CHID1 in lung cancer, it was studied in a mouse model of breast cancer." (PMID 33466316, 2021).
colorectal cancer (2 papers, 2023). A primary or metastatic malignant neoplasm that affects the colon or rectum. "In another study, AIF1 expression was positively correlated with another protein, chitinase domain-containing protein 1 (CHID1), which has been associated with macrophage infiltration in colorectal cancer patients and a favorable prognosis in NSCLC patients." (PMID 37237507, 2023). "High CHID1 levels are associated with low survival rate and poor survival prognosis in colorectal cancer patients." (PMID 37981907, 2023).
Alzheimer disease (1 paper, 2021). A progressive, neurodegenerative disease characterized by loss of function and death of nerve cells in several areas of the brain leading to loss of cognitive function such as memory and language. "CHID1 represents a new chitinase potentially involved in the principal processes underlying Alzheimer’s disease." (PMID 33924468, 2021).
emphysema (1 paper, 2014). "Among COPD subjects with ≥10% emphysema, chromosome 11p15.5, which includes genes AP2A2, MUC6 and CHID1, was the most significant region (rs7483870, β = 0.16L, P = 3.93 × 10−7; rs4076950, β = 0.13L, P = 2.88 × 10−6; rs4963123, β = 0.13L, P =3.40 × 10−6)." (PMID 25134640, 2014).
rheumatoid arthritis (1 paper, 2021). A chronic, systemic autoimmune disorder characterized by inflammation in the synovial membranes and articular surfaces. "Expression of CHID1 in pathology was demonstrated for blood monocytes of rheumatoid arthritis patients and in some other inflammatory diseases." (PMID 33466316, 2021).
squamous cell carcinoma (1 paper, 2021). A carcinoma arising from squamous epithelial cells. "At the same time, cytoplasmic expression of CHID1 was observed in tumor cells both in adenocarcinoma and in squamous cell carcinoma." (PMID 33466316, 2021).
ZIKV infection (1 paper, 2020). "For example, the alternative splicing of SLC35B6, MFSD8, and CHID1 might affect ZIKV infection." (PMID 32380717, 2020).
tumor (6 papers, 2014 to 2026). "A single-cell analysis showed tumor-associated expression patterns of CHID1 across malignant samples." (PMID 41869455, 2026). "At the same time, macrophage markers iNOS and CHID1 were found to be expressed in tumor cells and associated with prognosis." (PMID 33466316, 2021). "Expression of two TAM markers, iNOS and CHID1, was also analyzed in tumor cells, and their association to prognosis was established." (PMID 33466316, 2021). "We found CD68+, CD163+, CD206+, CD204+, and CHID1+ TAMs mainly distributed in the tumor stroma and tumor nest." (PMID 33466316, 2021). "Immunohistochemical analysis revealed granular cytoplasmic expression of CHID1 in all macrophages, both in the tumor stroma and in tumor nests." (PMID 33466316, 2021). "Observed expression pattern of CHID1, iNOS, IDO1, and PD-L1 prompted us to analyze the association of the expression of these markers in tumor cells with tumor characteristics." (PMID 33466316, 2021). "While the expression of CD163 in tumor cells is a marker of poor prognosis, high CHID1 expression is a marker of favorable prognosis." (PMID 33466316, 2021). "The tumor samples were stained for M2 marker CHID1 and M1 markers inducible nitric oxide synthase (iNOS) and IDO1." (PMID 33466316, 2021). "This may be an indication of different tumor-suppressing mechanisms of action of CHID1 and iNOS that have an additive effect on the tumor progression." (PMID 33466316, 2021). "Similarly to CHID1, expression of iNOS is documented for TAMs and tumor cells in different types of tumors, including NSCLC, but there is no clear association to prognosis established." (PMID 33466316, 2021). "At the same time, macrophage markers expressed by tumor cells may be considered as targets for anti-tumor therapy or, as in the case of CHID1, as potential anti-tumor agents." (PMID 33466316, 2021). "Expression of CHID1 is documented for TAMs in various tumors, but its role in tumor development remains unclear." (PMID 33466316, 2021). "Analysis of the expression of CHID1, iNOS, IDO1, and PD-L1 in tumor cells was done using immunohistochemistry." (PMID 33466316, 2021). "The tumor samples were stained for CD68 (total macrophage marker), CD163, CD206, CD204, CHID1 (M2 markers), inducible nitric oxide synthase (iNOS), IDO1 (M1 marker), FoxP3 (Treg marker), CD3 (mature T-cells marker), CD8, and PD-L1." (PMID 33466316, 2021). "Expression of iNOS was found in 74% of samples, expression of CHID1 was found in 100% of cases, expression of IDO1 was found in 60% of samples, and expression of PD-L1 was found in 96% of samples when a cut-off of 1% of positive tumor cells was used." (PMID 33466316, 2021).
infection (3 papers, 2020 to 2024). The state of being infected such as from the introduction of a foreign agent such as serum, vaccine, antigenic substance or organism. "Interestingly, however, in DENV2 infection, we determined small but significantly different changes in exon inclusion/exclusion levels in CHID1, SRSF2, HNRNPDL, and RBM39." (PMID 32380717, 2020).
adenocarcinoma (2 papers, 2021 to 2023). A common cancer characterized by the presence of malignant glandular cells. "High expression of CHID1 in contrast was found predominantly in adenocarcinoma (p < 0.0001) and in tumors of peripheral localization (p = 0.0001)." (PMID 33466316, 2021). "Analysis of prognostic value of high CHID1 expression showed that it was a marker of good prognosis in adenocarcinoma (HR = 0.3196, p = 0.0127) and in NSCLC in general (HR = 0.4019, p = 0.0115)." (PMID 33466316, 2021). "Similarly, high CHID1 expression is a marker of good prognosis in adenocarcinoma and in NSCLC in general." (PMID 33466316, 2021). "In summary, for the first time, we demonstrated that chitinase-like protein CHID1 can be expressed by NSCLC cells, and its high expression is a marker of good prognosis for adenocarcinoma and NSCLC in general." (PMID 33466316, 2021). "For the first time, we demonstrated that CHID1 can be expressed by NSCLC cells and its high expression is a marker of good prognosis for adenocarcinoma and NSCLC in general." (PMID 33466316, 2021).
cancer (2 papers, 2022 to 2023). A tumor composed of atypical neoplastic, often pleomorphic cells that invade other tissues. "However, in relation to cancer pathology and prognostication, there is precedence for the relevance of BCCIP or CHID1." (PMID 37981907, 2023).
neurological diseases (2 papers, 2020 to 2021). "HNRNPDL and RBM39 function in transcriptional regulation, HNRNPDL and SRSF2 regulate alternative splicing, MPRIP is involved in stress granule formation, CHID1 has a role in pathogen sensing, and KIF21A has been implicated in neurological diseases." (PMID 32380717, 2020). "Indeed, while the levels of CHI3L1 and CHI3L2 in AD patients tend to increase leading to hypothesis of a potential immunological role, CHID1 levels tend to decrease both with age and in neurological diseases such as AD." (PMID 33924468, 2021).
CHID1 also shares sentences with these, for which no sentence is quoted: non-small cell lung carcinoma (2 papers); glioblastoma (1); hepatocellular carcinoma (1); lung carcinoma (1); neuroblastoma (1); neurodegenerative disease (1).